UCA1 (urothelial cancer associated 1)
Diseases named in the same sentence as UCA1 in open-access papers (continued):
Sharing a sentence is not in itself a finding about the gene and the disease.
gastric cancer (continued). "Five lncRNAs, including AK001058, INHBA-AS1, MIR4435-2HG, UCA1 and CEBPA-AS1 were validated to be increased in gastric cancer tissues." (PMID 28423525, 2017). "LncRNA UCA1 (ENST00000397381.4) is the star biomarker in various types of cancers, such as breast cancer, gastric cancer, and lung cancer." (PMID 28970820, 2017). "LncRNA UCA1 is generally regarded as an oncogene, and it is usually highly expressed in a variety of cancers, such as OSCC 10, melanoma 16, gastric cancer 17, and breast cancer." (PMID 29125238, 2017). "The molecular mechanism of UCA1 suggested that UCA1 regulates the PI3K-Akt-mTOR signaling proteins and their downstream mediators, to alter gastric cancer progression in vitro and in vivo." (PMID 29212166, 2017). "In gastric cancer, overexpressed UCA1 has been found in tumor tissues compared with paired non-cancerous samples, and the function of UCA1 have been confirmed to contribute to the cancer cell migration, invasion and drug resistance." (PMID 31272462, 2019). "Similarly, overexpression of UCA1 induced by SP1 was reported to promote cell proliferation via recruiting EZH2 and activating AKT pathway in gastric cancer." (PMID 29719612, 2018). "The clinicopathological value of UCA1 in gastric cancer and hepatocellular carcinoma was not obtained for the limited and unavailable data of clinical pathological features." (PMID 28380443, 2017). "Bioinformatic analysis demonstrated two possible binding sites of mirR-27b in lncRNA UCA1 and in vivo analysis of gastric cancer tissues confirmed the negative correlation between lncRNA UCA1 and miR-27b expression." (PMID 28969100, 2017). "Using gastric cancer patients’ tumor tissues and paired adjacent non-cancerous tissues, the expression of UCA1 was shown to be highly correlated with the TNM stage and metastatic properties." (PMID 29212166, 2017). "In gastric cancer tissues, UCA1 expression was higher than the average level of adjacent non-cancerous tissues." (PMID 29212166, 2017). "The expression level of lncRNA UCA1 was determined in 102 paired gastric cancer tissues and adjacent non-cancerous tissues by qRT-PCR." (PMID 29212166, 2017). "The results showed that compared with adjacent non-tumor tissues, the expression of UCA1 showed a significant gradual increase from the TNM (I/II) to the TNM (III/IV) stages of gastric cancer." (PMID 29212166, 2017). "In addition, a clinicopathologic analysis revealed that UCA1 levels correlated with worse differentiation, greater tumor size and invasion depth, and TNM stage in gastric cancer." (PMID 27329842, 2016). "UCA1 accelerated cell proliferation and inhibited cell apoptosis through sponging miR-145 to upregulate MYO6 expression in gastric cancer, indicating that the UCA1/miR-145/MYO6 axis may serve as a potential therapeutic target for gastric cancer." (PMID 34238213, 2021). "To assess the biological role of UCA1 in gastric cancer, we constructed lentivirus vectors that overexpressed UCA1 or an siRNA vector that downregulated UCAI expression, then used these vectors to infect the human gastric cancer cell line, BGC-823, according to the manufacturer’s instructions." (PMID 29212166, 2017). "The results of the present study showed that the expression of UCA1 was significantly different during a gastric cancer TNM stage and lymph node metastases level, suggesting that high expression of UCA1 may play a role in activation of gastric cancer invasion and metastasis." (PMID 29212166, 2017).
gastric cancer (continued). "In a subgroup analysis of cancer sites, significant negative associations were found between levels of UCA1 and OS in the following cancers: colorectal (HR2.61, 95% CI1.56–4.37), NSCLC (HR1.49, 95% CI1.16-1.90), gastric cancer (HR2.19, 95% CI1.36–3.51), and ovarian cancer (HR1.89, 95% CI1.14–3.12)." (PMID 27329842, 2016). "Besides that, our results also showed that there was a significant negative association between UCA1 levels and DFS in digestive system malignancies (HR = 2.50; 95 % CI = 1.30–3.69; p<= 0.001), particularly in gastric cancer (HR =2.54; 95 % CI = 1.09–4.00, p= 0.001)." (PMID 28380443, 2017). "Subsequently, we compared UCA1 expression and gastric cancer patients’ clinical pathological features, and showed that UCA1 expression was correlated with the gastric cancer TNM stage and lymph node metastases, but was not correlated with other gastric cancer clinical pathological features." (PMID 29212166, 2017).
breast cancer (119 papers, 2014 to 2025). A primary or metastatic malignant neoplasm involving the breast. "The lncRNA UCA1, for example, has been associated with drug resistance in several cancers, including bladder and breast cancer." (PMID 40149330, 2025). "The urothelial cancer-associated 1 (UCA1) lncRNA is involved in the development and progression of bladder, colon, stomach, lung, and breast cancers." (PMID 41068676, 2025). "Urothelial cancer associated 1 (UCA1) is a hypoxia-responsive lncRNA whose expression is upregulated in breast cancer tissues." (PMID 37583933, 2023). "We show that UCA1 is commonly upregulated in hypoxic breast cancer cells and its overexpression is associated with tumor growth and inhibition of apoptosis in an HIF-dependent manner." (PMID 34054950, 2021). "Overall, these findings indicate that UCA1 is a hallmark of hypoxic breast cancer and its expression is positively regulated by HIF-1α." (PMID 34054950, 2021). "Although the role of lncRNA-UCA in cancer growth has been documented, the signaling pathways underlying UCA1 in hypoxic breast cancer are poorly elucidated." (PMID 34054950, 2021). "We showed that, under hypoxic conditions, the expression of UCA1 was increased in MCF-7 breast cancer cells, and this overexpression was associated with significantly increased expression of Ca-IX and NDRG1, which are known as markers of hypoxia." (PMID 34054950, 2021). "For instance, the high expression of urothelial cancer associated 1 (UCA1) in breast cancer EVs correlates with tamoxifen resistance." (PMID 33317058, 2020). "Urothelial carcinoma associated 1 (UCA1) was suggested to serve as a biomarker of several solid cancers including bladder cancer, breast cancer, gastric cancer and CRC." (PMID 28418892, 2017). "The long non-coding RNA (lncRNA) urothelial carcinoma-associated 1 (UCA1) has been recently shown to be dysregulated and plays important roles in progression of breast cancer." (PMID 27977766, 2016). "LncRNA urothelial carcinoma-associated 1 (UCA1) also served as a risk factor for indicating poor prognosis of breast cancer patients and silencing LncRNA UCA1 could attenuate cell proliferation and invasion." (PMID 37365581, 2023). "Urothelial carcinoma-associated 1 (UCA1) is a lncRNA known as oncogenic in breast cancer." (PMID 36358625, 2022). "Another highlighted lncRNA is the urothelial carcinoma-associated 1 (UCA1) transcript, which may also enhance tamoxifen resistance and is correlated with breast cancers outcome." (PMID 34359587, 2021). "In addition, exosomes-mediated transfer of lncRNA urothelial cancer associated 1 possess the ability to enhance tamoxifen resistance in estrogen receptor-positive breast cancer cells." (PMID 33585440, 2020). "The expression of lncRNA UCA1 was also reported to cause tamoxifen resistance in breast cancer." (PMID 31319040, 2020). "In the present study, we identified association between UCA1 and miR-122-5p in breast cancer cells." (PMID 29669595, 2018). "Therefore, UCA1-associated ER and Wnt/β-catenin signaling contribute to breast cancer progression via tamoxifen resistance." (PMID 29299178, 2017). "The UCA1 gene encodes for an lncRNA that is highly expressed in various carcinomas including bladder-, colorectal- and breast cancer, suggesting that UCA1 might serve as a potential biomarker for diagnostic purposes in the future." (PMID 27608009, 2016). "Moreover, UCA1 has been implicated in hormone therapy resistance in breast cancer cells as it sponges miR-18a, leading to HIF1α activation or inhibition of mTOR signaling, suggesting its multiple functions in breast cancer metabolism." (PMID 33123488, 2020). "Among the numerous lncRNAs implicated in drug resistance, MALAT1, UCA1, CYTOR, and HOTAIR have emerged as crucial oncogenes, and GAS5 is a well‐known lncRNA that acts as a tumor suppressor in breast cancer." (PMID 41031251, 2025).
breast cancer (continued). "In breast cancer, UCA1 induces tamoxifen resistance by activating critical oncogenic signaling pathways, including the mTOR and Wnt/β‐catenin pathways." (PMID 41031251, 2025). "Among the most studied lncRNAs in breast cancer are HOTAIR, UCA1, and MALAT1, which have been strongly implicated in tumorigenesis, metastasis, and therapy resistance." (PMID 40781106, 2025). "TGF-β was found to upregulate AC026904.1 and UCA1, two lncRNAs highly expressed in advanced breast cancer, via Smad and ERK pathways, respectively." (PMID 38254782, 2024). "The track record of UCA1 in the literature is extensive and suggests oncogenic functions in breast cancer." (PMID 38277283, 2024). "UCA1 also interacted with miR-122-5p to promote breast cancer growth via invasion and cellular proliferation by up-regulating its target genes via RNA binding protein and inhibiting the HER3 kinase UTR." (PMID 37245177, 2023). "There was remarkable UCA1 upregulation in tamoxifen-resistant breast cancer relative to sensitive samples." (PMID 37596669, 2023). "Mechanistically, UCA1 reduced m6A modification in breast cancer cells in a DNA methylation modification manner." (PMID 37901333, 2023). "Tamoxifen-resistant breast cancer cells upregulate UCA1 in contrast to tamoxifen-sensitive breast cancer cells." (PMID 36499136, 2022). "Particularly, in breast cancer cells UCA1 was demonstrated to repress p27Kip1 mRNA translation by competitively interacting with hnRNP I." (PMID 35456025, 2022). "A number of studies have shown high levels of lncRNA UCA1 in breast cancer tissues, which resulted in tumourigenesis through inhibition of tumour suppressor miRNA-143." (PMID 36685962, 2022). "The relative expression of different lncRNAs studied such as ANRIL (3.83 fold), TUG-1 (7.64 fold), UCA-1 (7.82 fold), and HIT (3.46 fold) and their association with clinical and pathological characteristics among the breast cancer patients (, –5) was obtained." (PMID 35132340, 2022). "In breast cancer cell lines, the expression of lncRNA UCA1 was found to be significantly increased under hypoxic conditions, and the proliferative and anti-apoptotic abilities of breast cancer cells were also increased." (PMID 36139386, 2022). "For instance, an elevated expression of lncRNA UCA1 under the influence of macrophages infiltration was measured and correlated with the advanced breast cancer clinical stage." (PMID 36685962, 2022). "UCA1 has been shown to be overexpressed in several breast cancer cells, including MCF-7, LM2-4, and MDA-MB-231." (PMID 34054950, 2021). "Our study shows that, under hypoxic conditions, UCA1 is overexpressed in several breast cancer cells—SKBR3, MDA-MB-468, MDA-MB-231, and BT474—compared with normoxic conditions." (PMID 34054950, 2021). "ARID1A is a key neoplasm suppressor gene that cooperated with CEBPα inhibited UCA1 transcription in breast cancer." (PMID 33592583, 2021). "Taken together, these findings suggest that HIF-1α-induced UCA1 overexpression is involved in the promotion of cell viability and inhibition of apoptosis in hypoxic breast cancer cells." (PMID 34054950, 2021). "The aim of this study was to investigate the expression of lncRNA-UCA in various breast cancer cell lines under hypoxic conditions and elucidate the role of UCA1 in tumorigenesis." (PMID 34054950, 2021). "In breast cancer, UCA1 expression was positively correlated with AKT expression, the activation of PI3K/AKT pathway can be regulated by UCA1 to confer tamoxifen resistance in cancer." (PMID 33743811, 2021). "It is reported that UCA1 can modulate the cell growth and apoptosis of breast cancer by downregulating the expression of microRNA-143." (PMID 33743811, 2021). "Their results showed that the regulation of PTP1B by UCA1 was involved in the proliferation of breast cancer cells." (PMID 34527584, 2021).
breast cancer (continued). "Our results show that exposure of MCF-7 cells to DMOG significantly increased the expression of UCA1, providing additional evidence that UCA1 expression in breast cancer is under the control of HIF-1α." (PMID 34054950, 2021). "In the present study, we first studied the expression of UCA1 in the MCF-7 breast cancer cell line under both normoxic and hypoxic conditions." (PMID 34054950, 2021). "To investigate the cellular function of UCA1 in breast cancer cells under hypoxic conditions, we transfected MCF-7 using siRNAs against UCA1, achieving 87% downregulation of UCA1 expression." (PMID 34054950, 2021). "The current study is the first to reveal that UCA1 is upregulated in hypoxic breast cancer cells and tumor tissues, promoting cell proliferation and inhibiting apoptosis." (PMID 34054950, 2021). "UCA1 knockdown induces inhibition of breast cancer cell proliferation and apoptosis under hypoxic conditions." (PMID 34054950, 2021). "The aim of this study was to explore the expression of UCA1 in hypoxic breast cancer and its impact on tumorigenesis in low levels of oxygen." (PMID 34054950, 2021). "Exosomes mediated transfer of lncRNA UCA1 can considerably increase tamoxifen resistance in estrogen receptor (ER)-positive breast cancer cells." (PMID 31956359, 2020). "Long non-coding RNA UCA1 can up-regulates PTP1B to enhance cell proliferation through sequestering miR-206 in breast cancer." (PMID 32248842, 2020). "As we described, lncRNA UCA1 was demonstrated to be involved in macrophage recruitment to promote breast cancer invasion in a previous study." (PMID 32190702, 2020). "In contrast, activated lncRNA UCA1 promoted macrophage infiltration, resulting in carcinogenesis and progression of breast cancer." (PMID 32190702, 2020). "For example, among the lncRNAs related to the endocrine therapy of breast cancer, HOX transcript antisense RNA (HOTAIR) is classified as an antisense lncRNA, while urothelial cancer associated 1 (UCA1) is a lincRNA." (PMID 32486413, 2020). "UCA1 induced tamoxifen resistance in breast cancer cells partly through activation of the mTOR pathway." (PMID 31143372, 2019). "PTP1B expression is positively corrected to UCA1 level in the breast cancer cells, both MCF-7 and MDA-MB-231 cell lines." (PMID 31695578, 2019). "While others have demonstrated that tamoxifen resistant breast cancer lines LCC2 and LCC9 has elevated levels of UCA1, the tamoxifen resistance is caused by induction of p-AKT/m-TOR pathway." (PMID 35582574, 2019). "UCA1 promotes the expression of Slug in breast cancer by directly titrating miR-1 and miR-203a at the post-transcriptional level." (PMID 31214490, 2019). "In this study, we investigated the mechanism of PTP1B over expression in breast cancer, that UCA1 sequesters miR-206, so that miR-206 cannot inhibit PTP1B expression any more." (PMID 31695578, 2019). "Recently, studies found that UCA1 was effective to enhance the activities of Wnt/β-catenin in several types of cancers including melanoma, breast cancer, osteosarcoma and oral squamous cell carcinoma." (PMID 31596734, 2019). "Some of these lncRNAs have been shown to be associated with the development of breast cancer, such as HOTAIR, UCA1, and LINC00518,30, 31 but the research on the role of lncRNAs in breast cancer is still very scarce." (PMID 30932362, 2019). "UCA1 down-regulation increased the tamoxifen sensitivity through inhibiting Wnt/β-catenin pathway in breast cancer cells while UCA1 up-regulation promoted EMT of breast cancer cells by activating Wnt/β-Catenin signaling pathway." (PMID 30918102, 2019). "We subsequently identified individual TEs within the promoters of breast cancer-associated genes and confirmed that TEs located upstream of SYT1, UCA1, AK4 and PSAT1 contributed promoter activity in TNBC cell lines." (PMID 31061680, 2019).